IL1B (interleukin 1 beta)
Diseases named in the same sentence as IL1B in open-access papers (continued):
Sharing a sentence is not in itself a finding about the gene and the disease.
periodontitis (continued). "Our previous studies and our present study have shown that periodontitis-associated LPS and MetS-associated SFA, such as PA, synergistically stimulate ASMase, leading to increased production of ceramide in macrophages and subsequent upregulation of inflammatory cytokines such as IL-6 and IL-1b." (PMID 37176029, 2023). "Our results could not discriminate mild from severe periodontitis, but in addition to IL-1β, RANK-L could be taken as a combined diagnostic biomarker for periodontitis." (PMID 36769650, 2023). "Of the studies included in this systematic review, four studies evaluated the levels of the pro-inflammatory cytokines IL-1β, IL-6, and TNF-α, the anti-inflammatory cytokine IL-10, and the matrix metalloproteinase-8 (MMP8), which is associated with the clinical manifestation of periodontitis." (PMID 37109642, 2023). "The aims of this study were (i) to assess whether the salivary IL-1β, IL-17A, RANK-L and OPG levels have the potential to discriminate between the mild and severe periodontitis conditions; and (ii) to enable diagnostic/prognostic actions to differentiate between distinct levels of the disease." (PMID 36769650, 2023). "Besides, there exists clinical evidence on the correlation of IL-1β with periodontitis." (PMID 37090158, 2023). "Moreover, NLRP6 induced pyroptosis of human gingival fibroblasts by activating caspase-1 and promoted the production of IL-1β, the level of which may reflect the severity of periodontitis." (PMID 37090158, 2023). "Moreover, these cytokines like TNF-α and IL-1β, which are produced from local periodontitis area, may reach the brain, and promote the AD pathology." (PMID 37635786, 2023). "Taking everything into account, IL-1B may be an important therapeutic target for periodontitis." (PMID 36429405, 2022). "We did not observe any significant association between IL-1B+3953 T/T genotype and periodontitis; this, however, may be due to a relatively low occurrence of this genotype in the evaluated sample." (PMID 36429405, 2022). "However, does increasing levels of IL-1β as a predictive and therapeutic biomarker, associate with increased severity of clinical periodontitis is not known." (PMID 35270581, 2022). "The periodontitis symptoms of mice in the F. nucleatum OMVs + ligation group were more serious than those of mice in the simple ligation group, with more osteoclasts and more inflammatory factors (IL-1β, IL-6, and TNF-α) being observed in their gingival tissues." (PMID 35391731, 2022). "Some reports have explained that a decrease in the levels of TNF-a, IL-1b, and IL-17 in the periodontal pockets of patients with periodontitis is observed following the treatment with the probiotic strain of L Lactobacillus reuteri, which may carry clinical significance." (PMID 35631603, 2022). "However, the exact mechanism that produces the TNF-α and IL-1β in periodontitis is still unclear." (PMID 35830121, 2022). "Activation of IL-1β signaling pathways promotes apoptosis, inhibits osteogenesis, activates osteoclasts, induces bone resorption and accelerates the progression of chronic inflammatory bone diseases such as rheumatoid arthritis, osteoporosis, and periodontitis." (PMID 35573242, 2022). "In our study, the expression of inflammatory cytokines in OSCC showed that periodontitis-associated bacteria significantly (p < 0.05) upregulated IL-6, TNF-α, IL-18, ASC (up to six times), and caspase-1 (up to four times) but downregulated NF-κB, NLRP3, and IL-1β (less than 0.5 times)." (PMID 34660289, 2021). "In an effort to explore possible downstream targets by which miR-146a may contribute to the pathobiology of disease, the levels of the main pro-inflammatory cytokines such as TNF-α, IL-1β, and IL-6 were studied in patients with chronic and aggressive periodontitis." (PMID 34645448, 2021).
periodontitis (continued). "Among these mediators, interleukin (IL)-1β has the capacity to trigger potent bone resorption, and IL-1β has been detected in the periodontal tissue and gingival crevicular exudates of patients with periodontitis, suggesting its involvement in alveolar bone resorption." (PMID 34830316, 2021). "Furthermore, an analysis conducted in the Japanese population revealed that individuals affected with both RA and periodontitis may display different distributions of IL-1B +3954 genotypes than healthy controls and subjects with periodontitis only." (PMID 34201546, 2021). "The induction of GSDMD in human periodontitis and ligature-induced rat periodontitis and the restorative effect of IL-1β antibody and caspase-4 inhibitor in rat periodontitis led us to hypothesize that GSDMD-driven pyroptosis was probably the key determinant of periodontitis." (PMID 33869229, 2021). "Therefore, IL-1β is an important therapeutic target for periodontitis." (PMID 35046930, 2021). "Therefore, it is challenging to suggest an absolute value of IL-1β for predicting periodontitis." (PMID 34199256, 2021). "Therefore, the authors concluded that periodontitis prevalence is higher in OSAS groups compared to the control group and OSAS is associated with periodontal indices and local inflammation parameters such as higher IL-1β." (PMID 34205812, 2021). "Interestingly, immunofluorescence analysis showed that PDLSCs (CD90+) were the source of IL-1β production and the amount of PDLSCs was decreased in periodontitis patients, which indicated the occurrence of pyroptosis in PDLSCs during periodontitis." (PMID 33869229, 2021). "Moreover, the expression of proinflammatory genes, such as Il1β, Il1α, Tnf and Ccl12, decreased in the 3D-exo-treated group compared with 2D-exo-treated group, indicating that the 3D-exos exerted enhanced anti-inflammatory efficacy in the periodontitis model." (PMID 34907166, 2021). "It is speculated that IL-1β be a potential therapeutic target for periodontitis." (PMID 31900383, 2020). "The ELISA results suggested that the concentration of interleukin-1 beta (IL-1β) in the icariin group was downregulated compared to the 0.9% NaCl group, which indicates that local injection of icariin relieved local inflammation in a minipig model of periodontitis." (PMID 29895944, 2018). "In addition, Tipton DA found that meth can significantly increase bacterial lipopolysaccharide (LPS)-stimulated IL-1β levels secreted by monocyte/macrophages, which could contribute to periodontitis in meth abusers." (PMID 29321070, 2018). "Because the progression of periodontitis is closely related with the expression of inflammatory cytokines such as IL-1β, -6, -8 and TNFα in gingival tissues, ET-1 could play important roles in the initiation and progression of the disease through the regulation of cytokine expression." (PMID 28030574, 2016). "However, it is unclear whether piperine suppresses pyroptosis and IL-1β release in the gingiva tissues of the periodontitis model." (PMID 27812336, 2016). "Thus, if inflammasomes and IL-1B are differentially expressed in periodontitis, there may be evidence for a hyper-responsive trait that leaves individuals prone to not only LAP but also CP and GAgP." (PMID 28008419, 2016). "The pivotal role of these cytokines in periodontitis is supported by reports that attachment loss is reduced in periodontitis patients with RA after anti-TNF treatment, and that local gingival administration of recombinant TNF-α or IL-1β exacerbates experimental periodontitis in rats." (PMID 26241961, 2015). "In addition, certain identified biomarkers, including IL8, IL1β, ICAM1 and VEGFA, were hub genes, therefore suggesting that they may be useful diagnostic markers for periodontitis." (PMID 25483140, 2015). "Also, IL-1β is regarded as a marker of inflammation as well as tissue destruction and may not therefore be directly predictive of disease progression in periodontitis." (PMID 24944840, 2014).
periodontitis (continued). "The detected in this study, following treatment with the probiotic strain of L. reuteri, decreased levels of TNF-α, IL-1β and IL-17 in periodontal pockets of patients with periodontitis may carry a clinical significance, preventing against progression of the disease." (PMID 24509697, 2014). "Therefore, it is reasonable to consider that the increased M1 polarization of macrophages during chronic periodontitis can be also a risk factor for AD, because the elevated levels of TNF-α and IL1-β are associated not only with the cognitive decline but also with the progression of AD." (PMID 24363500, 2013). "As IL-1β and TNFα are two of the important pro-inflammatory cytokines that contribute to inflammatory connective tissue degradation in periodontitis, we determined whether matrix metalloproteinases (MMPs) and tissue inhibitors of MMPs (TIMPs) were stimulated or inhibited by these cytokines." (PMID 23940616, 2013). "In addition, IL-1β stimulates many cells to produce MMPs and prostaglandins, resulting in bone resorption and connective tissue degradation, all of which contribute to the pathogenesis of periodontitis." (PMID 22315682, 2012). "However, in the active phase of periodontitis, IL-1β is produced by the host cells most likely during an extended period, which may simultaneously attenuate the metabolic activity of the A. actinomycetemcomitans biofilm." (PMID 21533109, 2011). "Among chemokines, CXCL2 was prioritized because it showed consistent upregulation across bulk periodontitis transcriptomes and IBD myeloid states, and it aligned with prominent IL-1β-chemokine signaling routes inferred from intercellular communication." (PMID 41624856, 2026). ", significantly attenuates key pro-inflammatory cytokines (IL-6, IL-1β, and TNF-α) at both the mRNA and protein levels in a rat periodontitis model." (PMID 41484074, 2026). "The results indicate that EVO exhibits potent antimicrobial activity against key periodontal pathogens and suppresses pathogen-induced ROS generation as well as the release of pro-inflammatory cytokines (IL-1β, IL-6, TNF-α) under periodontitis conditions." (PMID 42072113, 2026). "Periodontitis elevates circulating pro-inflammatory cytokines (e.g. TNF-α, IL-1β, IL-6), which can cross the blood–brain barrier, activate microglia and promote neuroinflammation—a process implicated in amyloid-beta accumulation and tau pathology." (PMID 41406907, 2026). "In the present study, MKE significantly decreased the levels of key inflammatory mediators such as iNOS, TNF-α, IL-6, IL-1β, COX-2, and mPGES-1 in the periodontitis-induced rat model." (PMID 41614939, 2026). "More studies are needed to investigate the role of other inflammatory cytokines (besides IL-1β), such as TNF-α, IL-6, RANKL, and OPG, in the inflammatory reaction of induced periodontitis and subsequent alveolar bone resorption." (PMID 40692535, 2025). "Compare differences of AD pathway molecules in healthy tissues and periodontitis tissues, including amyloid beta (A4) precursor protein (APP), a key gene in AD, interleukin-1 beta (IL-1β), and complement component 1 (q subcomponent, A chain) (C1QA)." (PMID 41170438, 2025). "In the rat model of ligature-induced periodontitis, expression levels of the proinflammatory cytokines TNF-α, IL-1β, and IL-6 in gingival tissue were significantly reduced in the E1 and E2 groups compared with those in the PC group." (PMID 40808155, 2025). "Within the limitations of this retrospective study, non-surgical periodontal therapy was associated with significant reductions in systemic inflammatory biomarkers (CRP, IL-1β, IL-6, TNF-α) across all stages and grades of periodontitis." (PMID 41440349, 2025). "Periodontitis has been shown to contribute to the development and progression of NAFLD through the mediation of inflammatory cytokines, including interleukin (IL)-1β, IL-6, and TNFα." (PMID 40142822, 2025).
periodontitis (continued). "The GCF total amount of IL-1β in the Stage II, III, and IV groups, however, were found to be significantly higher than periodontal health, gingivitis, and Stage I periodontitis group." (PMID 39964474, 2025). "Salivary and GCF Metrnl, IL-1β, and IL-10 levels were evaluated in patients with stage III periodontitis." (PMID 39964474, 2025). "Salivary levels of IgA, IL-1β, and MMP-8 were higher in patients with moderate to severe periodontitis compared with healthy controls." (PMID 41440367, 2025). "IL1B and CXCR4 are key regulators of inflammation and immune responses, garnering widespread attention for their roles in diseases like IBD and chronic periodontitis in recent years." (PMID 40002889, 2025). "Peptostreptococcus in periodontitis can stimulate various immune cells and produce TNF-α, IL-6, or IL-1β to trigger an inflammatory response, promoting bone resorption and causing irreversible destruction of the periodontium." (PMID 40387401, 2025). "While IL1A, IL1B, IL6, and TNFA are among the most extensively studied cytokine genes in periodontitis, numerous other pro- and anti-inflammatory mediators have been implicated in disease susceptibility, progression, and tissue destruction." (PMID 41300760, 2025). "Concurrently, host neutrophils in periodontitis lesions exhibit hyperactivation, secreting chemokines (e.g., CXCL8) and cytokines (e.g., TNF-α and IL-1β), which amplify monocyte recruitment and chronic inflammation." (PMID 41009952, 2025). "Apart from IL1B and CXCR4, various other immune-related cytokines play significant roles in the onset and development of IBD and periodontitis." (PMID 40002889, 2025). "IL-1β, IL-6, IL-17, IL-23, and TNF are well documented in periodontitis, having various roles in immune cell recruitment, pro-inflammatory activity, and periodontal tissue destruction." (PMID 41463036, 2025). "Exenatide downregulates IL-1β, inducible nitric oxide synthase (iNOS), and MMP-9 transcription in gingival tissues with periodontitis." (PMID 41328144, 2025). "Increased concentrations of IL-1β, TNF-α, and VEGF have also been observed in Grade C sites of Stage III periodontitis, reinforcing the link between cytokine expression and disease aggressiveness." (PMID 41440349, 2025). "This led to the following research question: What is the effect of closed-field scaling and root planning on serum levels of IL-1β, IL-4, IL-6, IL-8, IL-10, IL-12p70, IL-17A, VEGF, and TNF-α in patients with periodontitis and high blood pressure?" (PMID 40002786, 2025). "MLKL-mediated necroptosis in macrophages promotes the upregulation of TNF-α, IL-1β, IL-6, COX-2 and MMP9, contributing to alveolar bone resorption in mouse periodontitis models." (PMID 40307566, 2025). "In our study, IL1B, PTGS2, and SELL were significantly upregulated in both AAA and periodontitis compared to the control group." (PMID 40857330, 2025). "The proinflammatory cytokines and protease IL-1β, TNF-α, and matrix metalloproteinases (MMPs) are elevated in the saliva of periodontitis patients." (PMID 40418274, 2025). "In one oxidative stress–focused analysis, hub genes including CASP3, IL-1β, and TXN were shown to discriminate periodontitis subtypes with immune-correlated expression profiles." (PMID 40981157, 2025). "This chronic inflammatory state is primarily driven by cytokines or mediators including TNF-α, IL-1β, and PGE2, which are upregulated in both human periodontitis and EPD models." (PMID 41154468, 2025). "Previous studies have shown elevated levels of IL-1β, TNF-α, and matrix metalloproteinase-9 in gingival tissues from ligature-induced periodontitis models." (PMID 40863312, 2025). "In saliva, IL-1β and IL-6 were significantly elevated in T1DM patients, especially those with periodontitis (p < 0.001), with IL-1β also distinguishing T1DM individuals with gingivitis (p < 0.05)." (PMID 41280935, 2025).
periodontitis (continued). "The concentrations of IL-1β in GCF were found to be 116.55 pg/mL for healthy sites, 153.06 pg/mL for gingivitis sites, and 215.69 pg/mL for periodontitis sites at baseline." (PMID 41303313, 2025). "IF staining confirmed the enhanced expression of proinflammatory cytokines IL-1β and TNF-α in periodontitis tissues." (PMID 40307566, 2025). "It has been reported that ABMP increased NRF2 expression, alleviated gingival recession, reduced IL-1β and TNF-α levels, alveolar bone resorption, and osteoclasts number in periodontitis rat model." (PMID 40736688, 2025). "In the process of periodontitis, chemokines such as CXCL-8, CXCL-1, and CCL-5 and cytokines such as TNF-α, IL-1β, and IL-6 are present, due to the action of these multi-factors, it progresses to severe periodontitis with loss of periodontal support structures." (PMID 40733170, 2025). "The results showed that PA significantly reduced IL-1β, IL-6, TNF-α, CRP, and LPO levels and increased IL-10 levels in the periodontitis group; moreover, the histological analysis showed reduced inflammatory infiltrate and less fiber degradation." (PMID 40422620, 2025). "Pearson’s correlation coefficient also showed a direct and significant relationship between TNF-α and IL-1β salivary and GCF concentrations in patients with periodontitis or gingivitis." (PMID 40265034, 2025). "In conclusion, we identified IL1B, PTGS2, and SELL as key interacting genes in AAA and periodontitis through machine learning and various bioinformatics analysis methods, along with the significant roles of Tregs and neutrophils." (PMID 40857330, 2025). "This study compared tumor necrosis factor-α (TNF-α) and interlukin-1β (IL-1β) concentrations in the saliva and gingival crevicular fluid (GCF) of patients with gingivitis and periodontitis and healthy individuals." (PMID 40265034, 2025). "In periodontitis, it can be also released by periodontal ligament fibroblasts, T and B cells under pro-inflammatory stimuli (e.g. TNF-α, IL-1β, and IL-6) in the presence of LPS." (PMID 40736688, 2025). "As the results of immunohistochemistry showed, the pyroptosis-related protein levels of N-GSDMD, IL-1β, and IL-18, as well as the inflammatory factor TNF-α were significantly augmented in human periodontitis tissues compared with those in the healthy tissues." (PMID 40000642, 2025). "Increased IL-1β, IL-6, and TNF-α levels were also found in patients with periodontitis and AD suggesting the presence of overlapping mechanisms in the physiopathology of these diseases." (PMID 40736688, 2025). "Studies of neutrophils isolated from patients with chronic periodontitis report increased secretion of pro-inflammatory cytokines, i.e., IL-8, IL-6, TNF-α, and IL-1β." (PMID 39936030, 2025). "This inflammatory response manifests through substantial elevations in interleukin-1 beta (IL-1β), tumor necrosis factor-α (TNF-α), and interleukin-6 (IL-6) in periodontitis patients." (PMID 40869031, 2025). "Specifically, the persistent inflammatory response in periodontitis leads to the activation of immune cells, which secrete a wide array of pro-inflammatory cytokines, such as TNF-α, IL-1β, and IL-6." (PMID 39987090, 2025). "In mice with periodontitis, NAC-S2 decreased the expression of proinflammatory cytokines (TNF-α, IL-6, and IL-1β), reduced the distance between the cementoenamel junction and the bone crest, and alleviated TLR4/NF-κB-mediated inflammation." (PMID 41002732, 2025). "An increased risk of developing periodontitis is associated with genetic polymorphisms of IL1A, IL1B, IL6, and TNFA genes and MMP-9 (−1562C/T), ANRIL rs1333048, rs1333042, rs2891168, and rs496892 polymorphisms might have impact on susceptibility to periodontitis, especially in Caucasian individuals." (PMID 41300760, 2025). "Chronic periodontitis patients show an increase in the TNF-α, IL-6, IL-1B, and RANK-L levels and a decrease in OPG." (PMID 38817441, 2024).